BRCA1 (BRCA1 DNA repair associated)
Diseases named in the same sentence as BRCA1 in open-access papers (continued):
Sharing a sentence is not in itself a finding about the gene and the disease.
tumor (continued). "Although promoter methylation of BRCA1 and of BRCA2 gene has not been widely assessed in ovarian cancers, this mechanism is well known to affect other tumor suppressor genes, and, importantly, it is easy to detect in routine diagnostics even when FFPE tumor tissue is the only available material." (PMID 33352687, 2020). "When BRCA1 and/or BRCA2 is defective, nonhomologous end-joining (NHEJ) with no requirement for homologous template is an alternative process used to repair DSBs with potential genome instability, which accelerates tumor development." (PMID 32980867, 2020). "To generate a model in which Brca1-mediated transformation can be studied, we previously inactivated Brca1 alone in murine OSE, which resulted in an increased accumulation of premalignant changes, but no tumor formation." (PMID 20046869, 2009). "However, unlike revertible tumor suppressors such as BRCA1/2, some ATRi synthetic lethal partners (e.g., ARID1A) may be essential for tumor fitness, potentially limiting reversion-based resistance." (PMID 40869030, 2025). "Given that cell line collections are not representative of BRCA1‐ and BRCA2‐altered patient tumour response to PARP inhibitors, we hypothesised that an isogenic model hosting specific gene alterations would be more appropriate to explore cellular responses to PARP inhibitor treatment." (PMID 40977519, 2025). "Although baseline γH2AX in the biopsy from patient #3 was not evaluable due to inadequate viable tumor cell content, baseline γH2AX in the 6 evaluable cases was < 4.0% (range, 0.3–2.5% NAP), consistent with previous case series that were not selected for BRCA1/2 defects." (PMID 38010394, 2024). "Like in the olaparib arm, individual grafts that responded to CBP were predominantly BRCA1-foci-negative/RAD51-foci-negative and, interestingly, most grafts of the BRCA-foci-negative/RAD51-foci-positive model b3977, whose response to olaparib was mediocre, showed tumor size reduction under CBP." (PMID 37007122, 2023). "In this case, EO771 tumors with concurrent deletion of BRCA1 and STING responded strongly to combined olaparib and systemic DMXAA administered via IP injection in WT mice, thus showing that tumor cell-intrinsic STING is not critical for the therapeutic efficacy of this combination therapy." (PMID 35641483, 2022). "In BRCA1 mutant-HCC1937 xenografts, although we could not detect an induction of cell death by apoptosis, we could detect a reduction of ~24% (* p = 0.0488) of the tumor size upon olaparib monotherapy." (PMID 32630796, 2020). "Interestingly, BRCA1, BRCA2 andPALB2 heterozygous mice could not be distinguished from wild-type animals,corroborating the classic recessive model for tumor suppression, at least in animalmodels." (PMID 31067289, 2019). "Consistent with their tumour suppressor functions, FOXO3 depletion by siRNA accelerated cell proliferation when compared with the control cells transfected with non-silencing control siRNA and empty vector, whereas BRCA1 overexpression suppressed the cell proliferation." (PMID 27043660, 2016). "We identified only 18 CpG sites with different methylation levels between the three tumor groups in the discovery cohort, even at relatively nonstringent statistical significance (Kruskal-Wallis test, FDR = 10 %), and all of these CpG sites were located around the BRCA1 transcription start site." (PMID 26923702, 2016). "We tested levels of proliferation by MTT, clonogenic assays, and tumor growth of these isogenic cell lines, and found that the 92 J pair (92 J-shBRCA1 and 92 J- wtBRCA1) and MDA-MB-231 pair (MDA-MB-231-shBRCA1 and MDA-MB-231-wtBRCA1) exhibited similar growth, irrespective of their BRCA1 status." (PMID 24962108, 2014).
tumor (continued). "In circumstances when tumour samples are not available or the quality of the tumour material is inadequate for NGS, and a re-biopsy is challenging, then germline testing could be performed, with most laboratories currently undertaking panel testing of key germline HRR alterations including BRCA1/2." (PMID 36497408, 2022).
breast (56 papers, 2008 to 2025). "Germline BRCA1 variant was significantly associated with a poor DFS in the lymph node negative subgroup (HR = 5.4; 95% CI = 1.12–26.00; P = 0.04)." (PMID 27257965, 2016). "We also identified BRCA1 and PCNA to be specifically over-represented in LUAD lung lesions and markedly correlated with lung LUAD patient survival." (PMID 33097805, 2020). "Our data show relationships between negative ERCC1 or BRCA1 expression and clinical CRC LNM, implying that both ERCC1 and BRCA1 are involved in CRC metastasis, and that reduced expression of these proteins are early events in colorectal carcinogenesis." (PMID 23496813, 2013).
adenocarcinoma (40 papers, 2011 to 2025). A common cancer characterized by the presence of malignant glandular cells. "Our analysis of BRCA1/2 alterations across a large database of patients also revealed a BRCA reversion mutation in a patient with an adenocarcinoma of the gastroesophageal junction." (PMID 36418296, 2022). "We observed a higher mutation frequency of NF1, ATR, and BRCA1 in EGFR-mutant SCC compared to EGFR-mutant adenocarcinoma." (PMID 34195081, 2021). "Six BRCA1 variants were detected including a confirmed somatic mutation in adenocarcinoma (COSM6612515; Chr17: 41244952)." (PMID 32082376, 2019). "An increased risk of PC has been found in Ashkenazi Jews in whom more than 2% carry germline mutations in BRCA1 or BRCA2 and in PC with intraductal histology that appear to have greater genomic instability compared to those with adenocarcinoma histology." (PMID 36793600, 2023). "Adenocarcinoma was mostly observed in area of high BRCA1 mRNA expression and low BRCA1 IHC expression." (PMID 34820332, 2021). "MCF7 is an estrogen responsive, ER positive, adenocarcinoma cell line that expresses wild type BRCA1." (PMID 25460500, 2014). "In our previous study in resected NSCLC, we observed that BRCA1 expression was higher in squamous cell than in adenocarcinomas; in addition, in our experience, the expression of BRCA1 and EZH2 was significantly higher in small-cell than in NSCLC." (PMID 21951562, 2011). "Moreover, Rosell reported a significantly higher content of BRCA1 mRNA in SCCs than in adenocarcinomas." (PMID 28008145, 2017). "HCC1937 is a BRCA1-null, adenocarcinoma cell line that harbors the 5382insC mutation in the BRCA1 gene and is ER negative." (PMID 25460500, 2014). "Apparently, the expression of these genes did not predict for the outcome of adenocarcinoma patients in our series, in line with recent reports with immunohistochemistry for Ercc1 and Brca1." (PMID 22866924, 2012).
infection (28 papers, 2004 to 2025). The state of being infected such as from the introduction of a foreign agent such as serum, vaccine, antigenic substance or organism. "The top canonical pathways associated with the acute infection included “aryl hydrocarbon receptor signaling,” the “role of BRCA1 in DNA damage response” pathway, and the “activin-inhibin signaling” pathway (–log10[P] > 1.3, Benjamini-Hochberg–corrected)." (PMID 40662355, 2025). "Several cellular pathways that were affected early in infection were identified, i.e., eIF2 signaling, cell cycle, cholesterol biosynthesis, BRCA1-associated DNA damage response and cellular innate immune factors." (PMID 33630927, 2021). "As expected, VADs also strongly associated with sites identified by BRCA1 ChIP-seq at 16 hr post-infection (row 2)." (PMID 30028293, 2018). "To assess the relationship between cyclin B1 and BRCA1 deficiency, we restored cyclin B1 in MCF7 cells by infection with an Ad-cyclin B1, followed by knockdown of the BRCA1 gene." (PMID 30327455, 2018). "ChIP-seq analysis for γ-H2AX and BRCA1 demonstrated that DNA damage increased during infection, and MVM subsequently associated also with newly induced sites." (PMID 30028293, 2018). "During infection, the BRCA1 and DNA damage response pathway was active (48.75% of 80 genes) in MRC-5 cells." (PMID 33630927, 2021). "Among those are genes involved in BRCA1 and 2 regulatory networks, which for example are suppressed during infection of the monocytic THP-1 cell line with Mycobacterium tuberculosis to ensure its survival." (PMID 33513663, 2021). "Stable BRCA1 knockdown 293T cells were created by lentiviral infection using two independent shRNAs." (PMID 32826945, 2020). "Further, BRCA1 protein was decreased after LV-210 infection and increased after LV-In-210 infection." (PMID 30760709, 2019). "The HCC1937BRCA1 cell line was generated by infection of retrovirus containing the full-length wild-type BRCA1 and the control line was made using the empty vector-containing viruses." (PMID 31273285, 2019). "Much current research on BRCA1 focuses on its role in DNA damage repair, but its role in the context of immunology/infection is rarely characterized." (PMID 28487699, 2017). "PLA analysis revealed that BRCA1 knockdown abolished the acetylation of IFI16 during KSHV de novo infection." (PMID 27764250, 2016). "The IP results demonstrated that IFI16 and p300 interaction as well as IFI16 and H2B acetylation were inhibited in BRCA1 knockdown cells during KSHV de novo infection." (PMID 27764250, 2016). "The network analysis of suppressed infection markers centered on BRCA1 and BRCA2, which have roles in cell cycle control and DNA repair." (PMID 26214306, 2015). "For suppressed infection markers, one network (−log10p = 9) converging on BRCA1 and BRCA2 was identified." (PMID 26214306, 2015). "The BRCA1/2 network was suppressed during infection, suggesting that cell proliferation suppression is a feature of Mtb survival." (PMID 26214306, 2015). "More importantly, we have shown for the first time that BRCA1 is present at the HIV-1 LTR in infection and that LTR occupancy by the phosphorylated species is decreased upon treatment with ATMin." (PMID 25879655, 2015). "Reconstitution of BRCA1 expression in BRCA1-silent MCF7 cells via transient infection with Ad-BRCA1 partly restored vitamin D3 responsiveness and confirmed the role of BRCA1 in vitamin D3 growth inhibition." (PMID 25460500, 2014). "Infection by a lentiviral BRCA1 coding vector led to wt BRCA1 (HA-tagged) expression in primary BRCA1mut/+ cells." (PMID 25400221, 2014). "In our DEG data, BRCA1 showed a significantly decreased transcript expression at the acute stage of F. hepatica infection, which dropped down to an even lower level at the chronic stage of infection." (PMID 28487699, 2017).
infection (continued). "Furthermore, colocalization of H2B+STING PLA spots with IFI16+H2B and BRCA1+H2B spots (yellow spots and red arrows) suggested that the macromolecular complex formed between IFI16+H2B+BRCA1 is in close proximity with STING in the cytoplasm after infection." (PMID 27764250, 2016). "One can imagine that these and other viruses that access the nucleus during replication could feasibly interact with BRCA1 or BRCA2, driving the selection of variants that ultimately lead to decreased susceptibility to infection." (PMID 25011685, 2014). "We found that after infection with the BRCA14P virus, ~30% more cells were Fucci+ and therefore remained longer in S/G2/M compared to wild-type BRCA1 cells." (PMID 26320175, 2015). "IFI16, H2B, BRCA1 and cGAS knockdown clearly demonstrate that a macromolecular complex of these molecules is necessary for STING activation and innate IFN-β response during KSHV and HSV-1 de novo infection." (PMID 27764250, 2016). "BRCA1, BRCA2, FANCI, and FANCD2 were substantially downregulated following WT-H. pylori infection, but not upon infection with the ΔcagA H. pylori strain, highlighting the CagA-dependence in their downregulation." (PMID 35163588, 2022).
cardiovascular diseases (18 papers, 2014 to 2026). "This could be relevant in the context of our study, as there is emerging evidence on an association between BRCA1/2 deficiency and various cardiovascular disorders such as atherosclerosis and ischemic heart disease." (PMID 33543354, 2021). "Personalized early primary prevention and screening in BRCA1&2-carriers, may reduce the morbidity and mortality associated with cardiovascular disease." (PMID 31489114, 2019). "Recently, a causal part for the genes BRCA1 and BRCA2 in cardiovascular diseases was described." (PMID 33543354, 2021). "Future prospective studies in larger and distinct cohorts could further enable the validation of BRCA1 and CRISP2 to predict early cardiovascular disease." (PMID 28698603, 2017).
genetic disorders (16 papers, 2007 to 2025). "BRCA1-associated HGSOCs accounted for 48/63 (76%) patients with hereditary disease, while only 15/63 (24%) women were BRCA2 mutation carriers." (PMID 40547808, 2025). "Once identified, individuals at increased risk for one of the four selected genetic disorders are encouraged to undergo genetic counseling (21/21 for the four tests) or genetic testing for BRCA1/2 or LS (11/21), FH (5/11), or FT (4/10)." (PMID 32194621, 2020). "According to respondents, individuals at increased risk of one of the four selected genetic disorders are referred to genetic counseling by various healthcare workers; mostly by GPs, oncologists (BRCA1/2, LS), medical geneticists, genetic counselors, and gynecologists (BRCA1/2, LS, FT)." (PMID 32194621, 2020). "This is consistent with the error rates identified in EQA schemes for BRCA1/2, (Simon Patton, personal communication) and other inherited genetic disease." (PMID 28751759, 2017).
gastrointestinal tumors (10 papers, 2017 to 2024). "The three additional GI tumors with pathogenic germline BRCA1/2 mutations had a low HRD score and only one of them had high SBS3 exposure." (PMID 36964191, 2023). "While we were limited in sample size, our data indicate HRDetect that combines multiple genomic signatures may be more specific for identification of BRCA1/2-deficient tumors and platinum treatment duration compared to each signature individually, particularly in GI tumors." (PMID 36964191, 2023). "La ribonucleoprotein domain family, member-7 (LARP7), belongs to LARP RNA binding protein family and is BRCA1 ubiquitinase substrate regulating the metabolism and function of many RNA species and inhibit the occurrence of gastrointestinal tumors." (PMID 34107850, 2021). "Although most studies have shown that PARP1 inhibitors can effectively enhance the efficacy of chemotherapy drugs, the mutation rate of BRCA1 mutations in most gastrointestinal tumors is actually not high." (PMID 34497808, 2021). "However, the mutation rate of BRCA1 mutations in most gastrointestinal tumours is actually not high." (PMID 38009603, 2024).
benign tumor (8 papers, 2013 to 2023). "The frequency of BRCA1 methylation was significantly higher in the EOC samples than that observed in the benign tumor samples (P<0.001, Pearson’s χ2 test)." (PMID 24944674, 2014). "Even for BRCA1/2, the most common PGV, the proportion of VUS and benign tumors exceeded 70%." (PMID 37916805, 2023). "The rate of BRCA1 methylation was observed to be 35.2% (50/142) in the EOCs; however, no methylation (0/32) was observed in the benign tumors." (PMID 24944674, 2014). "Among the 32 cases of benign tumors; nine (28.1%) were negative and 15 (46.9%) were weakly positive, four (12.5%) were moderately positive and four (12.5%) were strongly positive for nuclear BRCA1." (PMID 24944674, 2014).
neurodegenerative disease (8 papers, 2007 to 2023). A disorder of the central nervous system characterized by gradual and progressive loss of neural tissue and neurologic function. "With DNA damage as a recognized feature associated with neurodegeneration, although specific mechanisms are unclear, BRCA1 as a DNA repair protein has been implicated in several neurodegenerative diseases." (PMID 34222870, 2021). "In accordance with this, BRCA1 has been implicated in the neuropathology associated with several neurodegenerative diseases, which will be highlighted in the following section." (PMID 34222870, 2021). "Together these studies emphasize a need for future research involving BRCA1, as it will not only provide further insights into DNA damage-induced senescence, but also introduce novel therapeutic avenues against neurodegenerative diseases and associated sex-specific differences." (PMID 34222870, 2021). "Breast cancer type 1 (BRCA1), a key DNA repair protein, has been associated with senescence as well as neurodegenerative diseases, however, its specific mechanisms remain unclear." (PMID 34222870, 2021). "With more specificity towards the central nervous system, BRCA1 also functions in the brain throughout neurodevelopment and adulthood, with its dysregulation reported in multiple neurodegenerative diseases." (PMID 37638313, 2023). "Previous studies have indicated that Brca1 (Breast cancer suppressor gene 1) plays an important role in neural development and degenerative diseases." (PMID 36430332, 2022). "It is unclear how BRCA1 dysregulation contributes more broadly to neurodegeneration as it seems differentially dysregulated across multiple neurodegenerative diseases." (PMID 34222870, 2021). "Overall, this evidence not only supports a dysregulation of BRCA1 in neurodegeneration, but suggests that its dysregulation in neurons and glial cells may vary between different neurodegenerative diseases." (PMID 34222870, 2021). "Other functions of BRCA1, including regulation of cell cycle and oxidative stress, which have also been suggested to be related to neurodegenerative diseases including AD, PiD, and PSP, may also be involved as suggested by other authors." (PMID 31861888, 2019). "However, Brca1 bioactivity is self-contradictory in neurodegenerative diseases." (PMID 36430332, 2022). "Thus, the transmission of mitochondrial damage to the nucleus, where it manifests as DNA double-strand breaks via the PINK1–Parkin–BRCA1 axis, may be relevant not only in the field of oncology, but also in the study of neurodegenerative diseases." (PMID 33888730, 2021). "Since DNA damage in neurons has been reported in various neurodegenerative diseases, including PiD and PSP, the mislocalization and coaggregation of BRCA1 with tau suggested in PiD and PSP in this study may also be involved in the progression of these diseases." (PMID 31861888, 2019).